LRRC24 (leucine rich repeat containing 24)
Synonyms: LRRC14OS
Tractability: Antibody: UniProt predicts a signal peptide or a membrane-spanning region; its Gene Ontology location is reachable by antibodies, with medium confidence. PROTAC: its protein half-life has been measured.
Gene: Protein-coding gene on chromosome 8 (144,522,388 to 144,527,033, reverse strand). Ensembl gene ENSG00000254402.
Subcellular location: Membrane
Subcellular location (Human Protein Atlas): Vesicles
Gene Ontology:
Molecular function: signaling receptor activity
Biological process: positive regulation of synapse assembly
Cellular component: external side of plasma membrane; plasma membrane; membrane
Genetic constraint (gnomAD): Loss-of-function variants: 17 observed, 12.14 expected, observed/expected ratio (o/e) 1.4, 90% interval 0.95 to 1.89. The synonymous counts are far from expectation, so gnomAD's model fits this gene poorly and the ratio says little. Missense variants: 847 observed, 603.43 expected, observed/expected ratio (o/e) 1.4, 90% interval 1.33 to 1.49. Synonymous variants: 447 observed, 292.35 expected, observed/expected ratio (o/e) 1.53, 90% interval 1.41 to 1.65.
Homologues: Orthologues: chimpanzee LRRC24 (98% identical), macaque LRRC24 (96% identical), pig LRRC24 (85% identical), dog LRRC24 (85% identical), mouse Lrrc24 (83% identical), guinea pig LRRC24 (83% identical), rat Lrrc24 (77% identical), tropical clawed frog lrrc24 (57% identical), zebrafish lrrc24 (55% identical), Drosophila melanogaster kek3 (21% identical), Caenorhabditis elegans sma-10 (20% identical), Drosophila melanogaster Con (18% identical), and 1 more. Paralogues in human: LRIG1 (26% identical), TRIL (26% identical), LRIG3 (25% identical), LRIG2 (24% identical), CPN2 (20% identical), LGR6 (20% identical), CHADL (19% identical), LGR4 (19% identical), LGR5 (19% identical), LRRTM2 (18% identical), LRIT1 (17% identical), LRRC26 (17% identical), and 10 more.
Diseases named in the same sentence as LRRC24 in open-access papers:
LRRC24 is named in the same sentence as 1 disease in open-access papers, as found by Europe PMC text mining. Sharing a sentence is not in itself a finding about the gene and the disease.
LRRC24 shares sentences with these, for which no sentence is quoted: neurodevelopmental disorder (1 paper).